AR (androgen receptor)
Diseases named in the same sentence as AR in open-access papers (continued):
Sharing a sentence is not in itself a finding about the gene and the disease.
metastatic disease (continued). "These cells lack AR expression, thus reproducing a phenotype detected in 23% of metastatic patients and 21% of metastatic tumors." (PMID 39858071, 2025). "By interrogating the GDC TGCA SKCM data set, we detect a correlation between increased expression of AR and metastatic disease." (PMID 39837817, 2025). "SDC shows characteristically high AR expression (78-96%) in primary and metastatic tumors (94% and 93%, respectively)." (PMID 40255718, 2025). "By studying the expression level of the AR in tumor tissues, we found that the AR is expressed to some extent in various types of tumors and related distant metastatic tumors." (PMID 40729027, 2025). "In a previous study, we showed that PARP7 expression is lower in metastatic tumors compared to primary tumors, and the difference is greater for AR+ metastatic tumors." (PMID 40681873, 2025). "With the exception of AR amplifications in castration-resistant and metastatic tumors, few alterations are enriched or consistently associated with metastatic disease alone." (PMID 38751776, 2024). "It has also been shown that, in PCa cells, the ubiquitination and degradation of AR by MDM2 can lead to AR(-) CSCs, which ultimately promote the occurrence of metastatic tumors." (PMID 37847340, 2024). "Because AR plays a key role in PCa progression, patients with metastatic disease recurrence are typically treated with AR-targeted therapeutics." (PMID 38383542, 2024). "Metastatic disease is initially responsive to androgen receptor signaling inhibition, but eventually resistance develops despite continuation of therapy." (PMID 38254784, 2024). "Landmark phase 3 trials demonstrated that adding chemotherapy (docetaxel) and androgen receptor pathway inhibitors to ADT significantly enhances overall survival, particularly for patients with high-volume, high-risk, or de novo metastatic disease." (PMID 39335158, 2024). "In AR-positive non-metastatic tumors, the expressions of miR-223-3p, miR-26a-5p, miR-26b-5p, and miR-489-3p were up-regulated." (PMID 38339416, 2024). "Androgen deprivation therapies along with androgen signaling inhibitors most likely extinguish the AR signaling in metastatic hormone sensitive prostate cancers and often these therapies lead to the development of castrate resistant metastatic disease." (PMID 38239314, 2023). "Androgen or androgen receptor-targeted therapies are standard care of treatment for locally advanced and metastatic disease, but therapy resistance is common." (PMID 36901912, 2023). "We observe there are no changes in PARP7 mRNA levels in primary tumors (TCGA-PRAD) compared with normal prostate cells (GTEx prostate), but the expression is reduced in metastatic tumors, and the difference is greater for metastatic tumors that are AR+." (PMID 37077937, 2023). "Clinical trials targeting these receptors in TNBC patients expressing high levels of ERβ, AR, or GR demonstrated moderate improvement of survival and patient outcome, particularly in patients with metastatic disease." (PMID 37835396, 2023). "Given PC’s dependence on androgens and the androgen receptor (AR) for growth, castration, either through surgery or medication, has been the backbone of treatment for metastatic disease." (PMID 37509723, 2023). "We compiled gene sets at the reprogrammed AR sites for two state transitions: tumorigenesis (healthy tissue to primary localized tumor) and metastasis (primary localized tumor to distant metastatic tumor)." (PMID 35509021, 2022). "In advanced and metastatic disease, the principal treatment involves systemically targeting the action of the androgen receptor (AR) using androgen deprivation or anti-androgens." (PMID 37435460, 2022).
metastatic disease (continued). "The differences in AR expression between primary and metastatic tumors suggest that AR should be detected in all patient biological materials, also considering the different role of this biomarker in the different subsets of disease." (PMID 36111296, 2022). "Metastatic disease must be treated systemically and here the role of the androgen receptor (AR) becomes paramount." (PMID 33572755, 2021). "Targeting the AR has drastically improved the prognosis of PCa patients, but a subset of tumors can become AR-indifferent and hence resistant to AR-targeting therapies, thus leading to fatalities through metastatic diseases that are treatment-resistant." (PMID 33525365, 2021). "The AR is a key player in PCa progression and the high AR transactivity facilitates the metastatic process and maintenance of metastatic disease." (PMID 34638338, 2021). "Extensive researches suggest that activation of AR-independent signaling pathways plays critical roles in the progression of metastatic disease and resistance to an AR antagonist." (PMID 34413914, 2021). "Despite ongoing development of novel approaches such as second generation androgen receptor targeted therapies, metastatic disease is still fatal." (PMID 33106940, 2021). "The AR signaling axis is a critical dependence for many early and late stage PCa tumors, making AR-directed therapies a front-line treatment for local and metastatic disease." (PMID 34208794, 2021). "Further studies to investigate AR pathway activity in metastatic tumors and to explore this therapeutic opportunity are warranted." (PMID 32230714, 2020). "Its growth mainly relies on the activity of the androgen receptor (AR), justifying the use of androgen deprivation therapy as a gold standard treatment for the metastatic disease." (PMID 32560058, 2020). "Blocking androgen receptor (AR) signaling is an effective treatment strategy for the treatment of advanced metastatic disease of PCa in men." (PMID 31217781, 2019). "The expression of EGFR was detected in the majority of serous adenocarcinomas of the ovary (i.e., 48 of 49 primary tumors; 11 of 11 metastatic tumors) and was also positively correlated with that of AR (i.e., r = 0.49, P < 0.001)." (PMID 30791431, 2019). "Western blotting analysis in serous carcinoma tissues also detected AR signals in 69% of primary tumors (n = 49) versus 45% of metastatic tumors (n = 11)." (PMID 30791431, 2019). "For example, β-catenin levels were reported to correlate with high Gleason score, AR expression and hormone-refractory metastatic disease." (PMID 29849951, 2018). "Initial treatment of metastatic disease is reliant on inhibiting androgen receptor (AR) signalling by systemic androgen deprivation therapy (ADT)." (PMID 29760584, 2018). "Neuroendocrine prostate cancer (NEPC) is becoming more prevalent as more potent androgen receptor (AR) pathway inhibitors are applied to patients with metastatic tumors." (PMID 28978002, 2017). "Increased AR activity has been shown to be preserved in spatially distinct metastatic tumors from the same patient suggesting the requirement for lineage-specific dependencies for metastatic castration resistant prostate cancer (mCRPC)." (PMID 29069718, 2017). "Subgroup analyses of non-metastatic disease also revealed a significantly higher survival rate in patients affected by AR-positive RCCs." (PMID 29108248, 2017). "To further test the feasibility of anti-AR therapy in TNBC metastatic disease, we studied AR status in TNBC lymph node metastases by mRNA and protein expression analyses." (PMID 24505496, 2014). "As a consequence, endocrine therapy involving androgen depletion by surgical or medical castration, as well as the blockade of the androgen receptor with anti-androgens, has become a standard treatment for advanced or metastatic disease." (PMID 21980429, 2011).
metastatic disease (continued). "In fact, among the steroid hormone receptors, AR is the best preserved one during metastases development and is expressed in the majority of metastatic tumors." (PMID 18507821, 2008). "The highest PYCR1 expression in our PCa samples was found in biopsies from metastatic tumors, possibly as a result of atypical AR activation." (PMID 17553165, 2007). "One common theme that has emerged from studies of metastatic disease is the central role of the androgen receptor in the development of androgen resistant disease." (PMID 17430594, 2007). "Lea and coworkers quantitated AR by immunohistochemistry in 1026 metastatic tumors and found that AR were present at double the frequency of PR." (PMID 16457685, 2005). "However, further research is needed to determine if FOXA1 Class 2 mutations emerge spontaneously during natural disease progression—such as in de novo metastatic tumors—or are instead induced by the selective pressure of androgen/AR blockade." (PMID 40570057, 2025). "Indeed, the AR gene is amplified in 50%–80% of ADT-treated metastatic tumors, which results in marked reprogramming of cistromic and cis-regulatory elements governing gene expression." (PMID 40906535, 2025). "We hypothesized that up-front pharmacologic blockade by use of AR antagonists alone with ADT would reverse the poor outcomes and survival associated with the adrenal-permissive HSD3B1 allele in patients with LV metastatic disease." (PMID 39286977, 2024). "Overall, these findings suggest that KDM5B is crucial for initial AR–dependent tumor growth and could also play a role in metastatic tumors once established." (PMID 37152294, 2023). "In addition to its role in DNA repair, DNA-PKcs plays a variety of transcriptional roles in AR-CRPC, where it was identified as a cofactor for the AR, and more recently, AR-Vs, and its high expression correlated with aggressive and metastatic tumors." (PMID 38201511, 2023). "Nonetheless, many patients with metastatic disease may benefit from combination therapy with an androgen receptor pathway inhibitor as well as GnRH agonist or antagonist therapy." (PMID 37835548, 2023). "In AR− metastatic tumors, PARP7 RNA levels are higher on average than AR+ tumors; this suggests AR status might help predict the utility of RBN2397 in a subgroup of patients." (PMID 37077937, 2023). "Subsequently, we assessed copy numbers of AR-FL and AR-Vs in primary and metastatic tumor samples." (PMID 37016463, 2023). "Likewise, no single gene differed in high-level amplification frequency between primary and metastatic BRCA2d tumors, although amplifications at AR were nominally more frequent in metastatic tumors (15.4% vs. 4.4%, padj = 0.03)." (PMID 35715489, 2022). "Previous data from STAMPEDE supports the use of docetaxel as an alternative to androgen receptor targeting in all newly‐diagnosed groups irrespective of metastatic disease risk group." (PMID 35411939, 2022). "However, androgen receptor (AR) targeting remains the most effective therapeutic option for most patients with metastatic disease." (PMID 36219867, 2022). "In another Phase II single-arm trial conducted in 146 AR-positive TNBC patients with inoperable locally advanced or metastatic diseases whose tumors had > 10% AR expression, a different AR inhibitor, abiraterone acetate plus prednisone, showed comparable results to bicalutamide." (PMID 35163586, 2022). "Alterations to the AR gene itself are largely restricted to the metastatic disease stage." (PMID 34208794, 2021). "Mutations in AR transcriptional cofactors and regulators may have influence, such as NCOA2 which is enhanced in 8% of primary and 37% of metastatic disease cases." (PMID 33599076, 2021). "In another phase 2 single-arm trial (UCBG 12-1), a different AR inhibitor, abiraterone acetate plus prednisone, was used to treat a cohort of 146 AR-positive TNBC patients with inoperable locally advanced or metastatic diseases whose tumors had ≥ 10% AR expression." (PMID 32846967, 2020).
metastatic disease (continued). "Since AR signaling persists in most cases of CRPC, patients receive further treatment with AR signaling inhibitors (abiraterone acetate, enzalutamide, apalutamide, and darolutamide) based on whether they have metastatic or non-metastatic disease." (PMID 33134178, 2020). "For example, PCa patients with SRD5A2 methylation may benefit less from intensified AR-directed therapy, or from early addition of docetaxel in castration-sensitive metastatic disease." (PMID 32134978, 2020). "Additionally, among patients with metastatic tumors that have amplified wild type AR, increased FOXC2 mRNA in tumors correlated with significantly reduced median overall survival." (PMID 31379747, 2019). "However, a significant portion of these men fail ADT after several years, resulting in castration-recurrent metastatic disease (mCRPC) that typically arises in the bone and lymph nodes, and that is largely driven by continued, often upregulated AR signaling." (PMID 28055971, 2017). "Apart from AR expression only metastatic disease was confirmed as a significant prognostic factor, whereas grade of malignancy, tumor extent, regional lymph node metastasis, the ECOG Performance Status, gender, and age were not correlated with the clinical outcome." (PMID 29108248, 2017). "Comparison of the primary and metastatic tumors revealed that PPP2R1A (E370X), SETD2 (I1608V), SMAD4 (G382T), and AR splicing site mutations may be specific to liver metastatic cancer." (PMID 27023146, 2016). "Focal amplification of AR (Xq12) is likewise common but restricted to metastatic tumors." (PMID 25520915, 2014). "Therefore, androgen ablation through blocking testicular production of androgens, and inhibition of AR function with antagonists constitute the principal systemic treatments for metastatic disease." (PMID 22403669, 2012). "In addition, it is remarkable that among the steroid hormone receptors, the androgen receptor is the best preserved one during metastases development and is expressed in the majority of metastatic tumors." (PMID 18507821, 2008). "If metastatic tumor with unknown primary in a female is AR positive, breast and ovary are the most likely primary sites." (PMID 17020615, 2006). "Such new treatments may be particularly important in metastatic disease, where the AR is often the sole steroid receptor expressed." (PMID 12439719, 2002). "Second‐generation AR pathway inhibitors (ARPIs), including non‐steroidal competitive antagonists such as enzalutamide, apalutamide and darolutamide, achieve more potent AR blockade than earlier agents (e.g., bicalutamide and flutamide) and have demonstrated survival benefits in metastatic disease." (PMID 41051130, 2025). "Indeed, we suspect that the increased use of effective agents impacting androgen receptor signaling may reduce the frequency of selecting taxane-based chemotherapy in the up-front approach to de novo metastatic disease since 2016." (PMID 37361592, 2023). "Notably, the pre‐treatment biopsies from 2 patients with metastatic disease, who demonstrated clinical responses to anti‐androgen therapy, showed AR expression and no AR splice variants." (PMID 31609094, 2019). "Therefore, assessing AR expression offers valuable prognostic information that could improve treatment selection for metastatic disease." (PMID 29108248, 2017). "In addition it has previously been reported that RTKs are extensively modified via N-linked glycosylation in the Golgi network prior to the insertion into the plasma membrane and signalling cross-talk between RTKs and the AR has been reported to contribute to metastatic disease." (PMID 23724116, 2013). "Interestingly, recent work from others and us has revealed that the AR pathway may be selectively attenuated in advanced/metastatic disease." (PMID 20976069, 2010).
metastatic disease (continued). "Recurrence or metastatic tumors are usually treated with androgen deprivation therapy (ADT) in the form of gonadotropin-releasing hormone (GnRH) and androgen receptor (AR) antagonists, so progression can be prevented and patient survival can be improved." (PMID 38794244, 2024). "In summary, our results indicate that the concurrent use of anti-AR therapy and OXPHOS inhibition has the potential to restrict drug resistance and hinder the progression towards metastatic disease." (PMID 38067315, 2023). "Although metastatic disease responds initially to first‐line androgen deprivation therapy (ADT), which blocks the androgen receptor (AR) signaling axis, development of castrate‐resistant prostate cancer (CRPC) is inevitable." (PMID 36811381, 2023). "In metastatic diseases, HF1beta positive cells in the epithelium and VEGF positive macrophages have significantly lower levels independently of the percentage of AR positive neoplastic epithelial cells." (PMID 33920263, 2021). "Despite initial good response to androgen deprivation therapy, most men with metastatic disease will eventually progress to castration-resistant prostate cancer (CRPC), where the androgen receptor (AR) axis still plays an essential role." (PMID 28486411, 2017). "Moreover, decreased levels of SRC expression were strongly associated with induced expression of AR pathway gene signatures by GSEA in the Taylor PCa dataset, which is composed of gene expression data from the tissue specimens of 111 PCa patients, including 98 primary and 13 metastatic tumors." (PMID 27028864, 2016). "Our results suggest that enhanced expression of Snail is important not only in the context of metastatic disease, but also in the setting of human CRPC by contributing to AR expression in response to AR-targeted therapies and thus resistance to AR blockade." (PMID 27409172, 2016). "These patients express low levels of AR and PSA but have been observed to exhibit explosive metastatic disease clinically." (PMID 24478054, 2014). "Another interesting candidate gene for the bypass of the AR pathway was the DKK3 tumor suppressor, which was down-regulated in PC346DCC and multiple databases of primary and metastatic tumors." (PMID 20976069, 2010). "In a highly plausible model, AR-negative cancer cells inhabiting metastatic tumors secrete IL-1β and the signaling by this cytokine elicits the production of tumor-promoting factors by the surrounding stromal cells via IL-1R stimulation." (PMID 39858071, 2025). "Enzalutamide, a second-generation androgen receptor inhibitor, is indicated for the treatment of metastatic disease, as well as in the treatment of non-metastatic castration resistant prostate cancer (PCa)." (PMID 38589645, 2024). "When revisiting the metastatic tumors stratified by APUC-6 levels, we found that tumors with high APUC-6 expression had increased expression of ESR1, ESR2, and PGR, but reduced expression of AR." (PMID 39207857, 2024). "The expression of miR-205-5p was also found to be up-regulated in metastatic tumors but was not different within AR-positive cases." (PMID 38339416, 2024). "In both AR+ and AR− metastatic tumors the expression of PARP7 and AR is not significantly correlated." (PMID 37077937, 2023). "Targeting RUNX1 may be an attractive strategy to potentiate the anti-tumor effects of AR inhibition, specifically in the slow-growing CSC-like populations that resist chemotherapy which lead to metastatic disease." (PMID 36766786, 2023). "In the setting of metastatic disease at presentation, systemic therapy with ADT and next-generation androgen receptor (AR) signaling inhibitors (ARSIs), such as enzalutamide, are a first-line therapy to prevent the reactivation of AR signaling." (PMID 38201511, 2023).